ADPRHL1 (ADP-ribosylhydrolase like 1)
Description:
Required for myofibril assembly and outgrowth of the cardiac chambers in the developing heart (By similarity). Appears to be catalytically inactive, showing no activity against O-acetyl-ADP-ribose (By similarity).
Synonyms: ARH2
Tractability: Antibody: the Human Protein Atlas places it where antibodies can reach. PROTAC: ubiquitination databases record sites on it.
Gene: Protein-coding gene on chromosome 13 (113,399,611 to 113,453,488, reverse strand). Ensembl gene ENSG00000153531.
Subcellular location: Cytoplasm, myofibril, sarcomere
Subcellular location (Human Protein Atlas): Plasma membrane; Nucleoli
Gene Ontology:
Molecular function: ADP-ribosylarginine hydrolase activity; magnesium ion binding
Biological process: cardiac chamber ballooning; cardiac myofibril assembly; protein de-ADP-ribosylation
Cellular component: sarcomere
Genetic constraint (gnomAD): Loss-of-function variants: 43 observed, 43.88 expected, observed/expected ratio (o/e) 0.98, 90% interval 0.77 to 1.26. The upper end of that interval is the gene's LOEUF score, 1.26, which puts it in group 5 of 6, group 1 being the genes least tolerant of losing a copy. Missense variants: 2,005 observed, 2,158.5 expected, observed/expected ratio (o/e) 0.93, 90% interval 0.89 to 0.96. Synonymous variants: 870 observed, 888.54 expected, observed/expected ratio (o/e) 0.98, 90% interval 0.93 to 1.04.
Homologues: Orthologues: macaque DCUN1D2 (82% identical), chimpanzee ADPRHL1 (81% identical), mouse Adprhl1 (41% identical), tropical clawed frog dcun1d2 (21% identical), zebrafish adprhl1 (12% identical). Paralogues in human: ADPRH (8% identical).
Diseases named in the same sentence as ADPRHL1 in open-access papers:
ADPRHL1 is named in the same sentence as 11 diseases in open-access papers, as found by Europe PMC text mining. Sharing a sentence is not in itself a finding about the gene and the disease. The quoted sentences say what the papers report.
breast carcinoma (1 paper, 2022). "As a result of our algorithm, we identified a signature of 5 CTC-specific genes, i.e., ADPRHL1, ELF3, FCF1, TFF1 and TFF3, and explored its clinical significance according to their expression in CTC-enriched blood samples in our breast cancer case series." (PMID 35216615, 2022).
cardiomyopathy (1 paper, 2023). A disease of the heart muscle or myocardium proper. "Significant differential imbalance between all four phenogroups was found for several SNPs located in genes with known cardiomyopathy links other than DCM such as posterior myocardial infarction, the top 5 hits were EZH1, NIBAN1, C7, CDIN1, and ADPRHL1." (PMID 36631531, 2023).
hypertrophy (1 paper, 2025). Hypertrophy is the increase in the volume of an organ or tissue due to the enlargement of its component cells. "ADPRHL1, a gene implicated in cardiac development, was upregulated in response to acute hypertrophy and downregulated in the chronic hypertrophy model." (PMID 40791945, 2025).
heart disease (3 papers, 2019 to 2023). "This suggests that the impact of ADPRHL1 deficiency on the heart is not limited to development, but also affects the normal physiological activities of the heart, potentially leading to heart disease." (PMID 37880701, 2023). "One encoded a missense (p.Leu294Arg) substitution in ADPRHL1 that additionally associated with genome-wide significance to an automated ECG diagnosis of a left anterior fascicular block (LAFB) conduction defect." (PMID 32726316, 2020). "Other genes have not been implicated in heart diseases (ADPRHL1, KLHL38, SH3BGR)." (PMID 31641117, 2019).
ADPRHL1 also shares sentences with these, for which no sentence is quoted: cancer (3 papers); Arrhythmia (1); cardiac conduction disorder (1); Cirrhosis (1); infection (1); tumor (1); uveal melanoma (1).